KRAS (KRas proto-oncogene, GTPase)
Diseases named in the same sentence as KRAS in open-access papers (continued):
Sharing a sentence is not in itself a finding about the gene and the disease.
tumor (continued). "From an updated multicenter study, including patients with EGFR mutated (EGFR+), Kirsten rat sarcoma (KRAS+) and EGFR/KRAS wildtype metastatic NSCLC, all patients with available formalin-fixed paraffin-embedded (FFPE) tumor samples were selected." (PMID 37213294, 2023). "In this study, we showed that knockdown of PDE4DIP impaired KRAS-mutant CRC tumor growth through suppression of oncogenic RAS/ERK/AKT signaling." (PMID 37355626, 2023). "NF-κB signaling in cancer and myeloid cells impacts modes of tumor progression and metastasis in various tumor types and is intimately addicted with oncogenic KRAS signaling." (PMID 36980752, 2023). "A comparison of the two models 15 weeks post-tumor initiation revealed fewer KRAS G12C tumors than KRAS G12D tumors above any minimum size cutoff." (PMID 37828026, 2023). "In the Xenopus laevis embryonic epithelium, clusters of KRAS-expressing cells form tumour-like structures characterised by high contractility and tension." (PMID 36175301, 2023). "As Th2 cytokines, IL4 and IL13 have been reported to restrain the immune response to tumor cells and promote the proliferation of KRAS-mutant cells." (PMID 36975441, 2023). "Despite the differences in oncogenic potential of KRAS G12C and KRAS G12D, the tumor suppressive effects at 15 weeks post-initiation were highly correlated (Spearman ρ = 0.92)." (PMID 37828026, 2023). "Although oncogenic KRAS can orchestrate immune evasion pathways, the response of KRAS-mutant tumours to ICB is still low [~ 25%], with perhaps the most reliable biomarker for response remaining TMB." (PMID 36864508, 2023). "MRTX1133 interacts with active and inactive KRAS G12D forms, and significantly reduces the growth of KRAS G12D–mutant tumor cell lines and patient-derived xenografts." (PMID 37655310, 2023). "Based on these data, we propose that KRAS-mutant cells must navigate a ferroptosis checkpoint by upregulating FSP1 during tumor establishment." (PMID 36443441, 2023). "Larvae with mosaic, transient expression of KRAS p.Gly12Asp or p.Gly13Asp (represented by mCherry) showed edema around the heart, fusion of the thoracic duct with cardinal vein, and tumor-like expansion of lymphatic tissue." (PMID 37154160, 2023). "In this study, we have used genetically engineered mice to compare the therapeutic efficacy and the emergence of tumor resistance between genetic ablation of mutant Kras expression and pharmacological inhibition of oncogenic KRAS activity." (PMID 36928090, 2023). "Previous research has demonstrated that tumor microenvironment (such as hypoxia), numerous growth factors, and carcinogenic-associated signaling pathways (such as TGF-β, Notch, MAPK, and KRAS signaling pathways), can activate the EMT process." (PMID 37051544, 2023). "Our results indicate that EUG interferes with major tumorigenic pathways involved in tumor metastasis, such as the KRAS pathway." (PMID 36831488, 2023). "This was supported by the observation that in an acidic TME, as is common in KRAS-mutant tumours due to the enhancement of the Warburg effect, VISTA can also bind PSGL-1, another potent inhibitor of T cell activity promoting an exhausted phenotype." (PMID 36864508, 2023). "Currently, to better predict the behavior of a tumor, genetic alterations in KRAS, v-RAF, BRAF and CDX2 are used to guide prognostication and optimize adjuvant treatment." (PMID 37762323, 2023). "Several oncogenic events, such as KRAS mutation or MYC activation, have also been shown to suppress or evade anti-tumour immune responses via immune checkpoint molecules." (PMID 37761948, 2023). "Another KRAS/STK11 mouse model study established tumor regression following T cell infiltration subsequent to IL-6 antibody administration, while the same models were irresponsive to PD-1 mAb." (PMID 36899885, 2023). "Herein, we observed that tumor‐specific cytotoxic T‐cells in KRAS mutant tumors were more sensitive to tumor‐mediated AICD, and thus displayed poor persistence." (PMID 36599679, 2023).
tumor (continued). "The codelivery of KRAS-Notch1 siRNA with GEM showed a synergetic effect leading to enhanced anti-tumour effect and apoptosis." (PMID 36635659, 2023). "While BRAF and KRAS mutations both lead to activation of the RAS-RAF-MEK-cascade, KRAS mutations occur during tumour progression in the classical pathway or suppressor pathway while BRAF mutations are initiating mutations in the sessile serrated pathway." (PMID 37344790, 2023). "Tumor-infiltrating B (TIB) cells produce KRAS mutation-specific IgG, and IgG1 monoclonal antibodies are able to interfere with the growth of tumors with KRAS mutations." (PMID 37529035, 2023). "CRC patients in the high ARG_score group tended to have a shorter RFS than that in the low ARG_score group (P < 0.001), as demonstrated by the results for age, sex, tumor location, TNM stage, and KRAS and BRAF mutations." (PMID 37938164, 2023). "We include recommendations for options in unselected patients and therapies that should only be offered in patients with distinct tumor profiles (e.g., BRAF mutations, KRAS G12C mutations, HER2 amplification, deficient MMR, or NTRK gene fusions)." (PMID 38201553, 2023). "In summary, our study indicates that aberrant HES1 expression correlates with tumor matrix remodeling in KRAS mutant CRC." (PMID 37749297, 2023). "YAP activation can compensate for KRAS inhibition in KRAS-driven murine models of cancer and enable KRAS-independent tumor growth." (PMID 37277530, 2023). "While previous studies have explored the prevalence of KRAS variants in CRC, to our knowledge, our research was the first to delve into the intersection of age of onset, tumor location, and KRAS sequence variation status." (PMID 38032636, 2023). "In line with the mutual exclusivity of BRAF and KRAS mutations, we only detected the BRAF V600E mutation in the analysis of the initial tumor." (PMID 36967525, 2023). "For 744 CRC cases, tumor tissue was available and successfully analyzed for the BRAF V600E mutation, KRAS mutations, or MSI status." (PMID 37849011, 2023). "In order to identify the molecular differences between TME of KRASmut and KRASwt, we determined the contrasting upregulation of DEGs between TME and cancer regions in each KRAS tumor type." (PMID 36831441, 2023). "By keeping tumor cells in the active mesenchymal state, uPAR promotes KRAS-driven proliferation and cell migration as a likely explanation for the poor prognosis of PDAC with high expression of uPAR." (PMID 36900379, 2023). "We discovered that KRAS was abundantly expressed in all tumor cell populations as well as in CAFs and T cells." (PMID 37007745, 2023). "The rational combination of immunotherapies and the lactic acid blockade was sufficient to establish a long‐term tumor‐specific T‐cell response in KRAS mutant tumors; this is of obvious therapeutic significance." (PMID 36599679, 2023). "Taken together, these data suggested that CD47 was involved in KRAS-driven tumor progression by restraining the antitumorigenic properties of macrophages." (PMID 36413402, 2023). "For intracellular molecules, there were significant expression of KRAS in all three tumor cell populations as well as in CAFs and T cells." (PMID 37007745, 2023). "A greater understanding of how oncogenic KRAS drives immune evasion and how mutant-specific KRAS inhibition impacts the tumor microenvironment can lead to novel approaches to combining RAS inhibition with immunotherapies." (PMID 37581538, 2023).
tumor (continued). "The variables taken into consideration are BRAF, KRAS, NRAS mutations, the expression of fibronectin, CXCR4, and FAP in terms of intensity in both the primary tumor and metastases, and the number of metastases." (PMID 37892020, 2023). "Together, these agents synergize, substantially enhance apoptosis, and trigger potent tumor regression in vivo, even in models that are relatively insensitive to KRAS G12C inhibition alone." (PMID 37384411, 2023). "uPAR and KRAS cooperate in switching the tumor from a dormant epithelial to an active mesenchymal state, which likely explains the poor prognosis of PDAC with high uPAR." (PMID 36900379, 2023). "Among the oncogenes, MUC16 (mutated in 18.9% of tumours), PIK3CA (12.4%), and KRAS (11.1%) were the most frequently mutated across the profiled samples." (PMID 37550388, 2023). "With the emergence of KRAS and BRAF mutations, resistance to EGFR-targeted therapy has developed, driven by mechanisms affecting both cellular pathways and the tumor microenvironment." (PMID 37762323, 2023). "Since the presence of protein activating mutations in KRAS and BRAF genes is very common in PM and tumour grade is a parameter that characterizes tumour cell behaviour, they are probably associated with specific mechanical characteristics." (PMID 37500685, 2023). "The post-operative pathology identified adenocarcinoma (pT4N2cM1) with KRAS/NRAS/BRAF wild-type MSS status in her tumor." (PMID 37681031, 2023). "Herein, we showed that anti-KRAS antibody treated tumor cells have less intense SOX9 cytoplasmic and nuclear staining compared to untreated cells." (PMID 37051535, 2023). "By downregulating the NF-κB pathway via proteasome inhibition, bortezomib induced tumor regression in KRAS G12D mutant mice models." (PMID 37569406, 2023). "In the present study, we investigated the prognostic value of the mutational status of the KRAS, NRAS, PIK3CA and BRAF genes detected in tumor biopsies and plasma samples from 51 synchronous metastatic colorectal cancer (SMCC) patients." (PMID 37176143, 2023). "STAT3 has been confirmed to perform a tumor suppressive role in KRAS-driven lung tumorigenesis 25,26." (PMID 36993454, 2023). "Thoracic lymphomas are often considered as an off-target effect of oncogenic KRAS and were excluded from subsequent survival and tumour-spectrum analyses." (PMID 37270580, 2023). "Several studies in various cancers, including pancreatic, have also indicated the role of overactivated KRAS in supressing the pro-apoptotic and tumour suppressor genes by enhancing the epigenetic modifications of histones." (PMID 37794133, 2023). "It has been shown that KRAS-G12D protein released from tumour cells undergoes ferrogenesis and is taken up by macrophages, leading to the conversion of macrophages to an M2-like suppressing-inflammatory pro-tumour phenotype." (PMID 36936437, 2023). "As indicated by tumor volume and weight, ACT therapy in KRAS wild‐type PDXs efficiently inhibited tumor growth." (PMID 36599679, 2023). "This supports the role of SLC25A22 in MDSC recruitment and activation in KRAS-mutant CRC to facilitate tumor growth." (PMID 37542037, 2023).
tumor (continued). "And MUC1-C inhibition contributed to an inhibition of MYC gene expression, tumor cell survival and tumor growth in KRAS mutant NSCLC cells." (PMID 36895477, 2023). "Preclinical models have demonstrated the selective inhibition of cell viability in KRAS-G12D mutant tumor cells with a long predicted half-life (~50 h)." (PMID 37662925, 2023). "B7-H4+ tumour status has been previously shown to co-express in KRAS-mutant NSCLC (76%) and other KRAS-mutant cancers such as CRC." (PMID 36864508, 2023). "In this study, we developed a transient ex vivo culture from CRC patients’ tumor and matched mucosa tissues as a model to test for anti-KRAS antibody internalization." (PMID 37051535, 2023). "It has been reported that Smurf2 appears to act as an oncogene, promoting tumor development through stabilization of KRAS and EGFR." (PMID 36611161, 2023). "While treatment of tumor cells with anti-KRAS antibodies led to an observable change of localization of KRAS from inner plasma membrane to cytoplasm, its effect on downstream signaling remains to be confirmed." (PMID 37051535, 2023). "Major signaling pathways, including mitogen-activated protein kinase (MEK), often characterize mutant KRAS tumor proliferation and survival, so inhibiting their signaling mechanism is a valid approach for overcoming these pathways." (PMID 37373999, 2023). "As for other anti-tumor therapy, it was also reported that patients with KRAS G13D usually presented an inferior response to chemotherapy." (PMID 38097680, 2023). "Inactivation of many genes that were functional tumor suppressors in KRAS-driven lung tumors, including Lkb1, Setd2, and Kmt2d, were deleterious in EGFR-driven lung tumors." (PMID 37828026, 2023). "As was the case for tumor growth effects, inactivation of most genes had similar effects on the number of KRAS G12C- and KRAS G12D-driven tumors." (PMID 37828026, 2023). "KRAS mutations increase levels of a protein called SIRT1, and this interaction boosts cancer cell proliferation and tumour growth." (PMID 37779142, 2023). "Moreover, a polygenic risk score that takes into account the interplay of multiple signaling pathways (e.g., the mutated KRAS gene and concomitant high expression of vascular endothelial growth factor) could likely better capture the tumor recurrence phenotype." (PMID 36900260, 2023). "Compared to untreated tumor control, treated tumor cells has reduced KRAS plasma membrane localization." (PMID 37051535, 2023). "Following this activation, macrophages fuel the tumor with interleukin (IL)-1β, to close an inflammatory loop through which KRAS-mutant cancers attract host immune cells to the tumor site to accelerate tumor growth and aggressiveness." (PMID 36980752, 2023). "When Cre was encoded by the heat-shock treatment via hsp70-Cre, it recombines two LoxP sites, removing the EGFP and expressing KRASG12D, resulting in KRAS-driven ERMS tumor in zebrafish." (PMID 37958442, 2023).
tumor (continued). "In several preclinical studies, these combinations are being pursued as KRAS G12C positive tumor cell lines exhibit an immunosuppressive environment attenuated by KRAS inhibition." (PMID 37970206, 2023). "Overactivation of KRAS signaling has been shown to enhance the secretion of interleukin-6, which is necessary for tumorigenesis and tumor development." (PMID 37457560, 2023). "For the top differentially occurring genes with KRAS, the co-alteration landscape was largely similar across KRASm isoforms, but distinct for KRAS WT within a given tumor type." (PMID 36494601, 2022). "A salient feature that distinguishes PDAC from other KRAS-mutant cancers is an extensive fibro-inflammatory stroma, which accounts for 80%–85% of the tumor bulk." (PMID 36465353, 2022). "KRAS mutant exosomes from tumor cells induce NETosis via IL8, leading to the enhanced cancer cell migration and invasion." (PMID 35574410, 2022). "Concomitant KRAS and BRAF mutations in GI tumors are rare, occurring in less than 0.001% of cases and are associated with an aggressive tumor behavior." (PMID 35586494, 2022). "Combination of SHP2, PI3K, and KRAS G12C inhibitors was found to induce durable tumor regression in EMT-induced mouse xenografts, which exhibit FGFR and IGF1R-induced MAPK and PI3K reactivation." (PMID 35267628, 2022). "KRAS is a pan-tumor oncodriver with alterations identified in 23% of over 400,000 adult cases, including 21% with mutations, similar to smaller published studies." (PMID 36494601, 2022). "Bioengineered exosomes loaded with siRNAs targeting genes involved in oncogenes like BCL-2, PLK1, KRAS, the survivin protein prevents cell migration and proliferation and forms a strong foundation of exosome mediated siRNA treatment to the tumor cells." (PMID 36362424, 2022). "We explored the connection between the clinicopathological characteristics and various tumor stages according to KRAS expression levels in different pathology grades." (PMID 36330448, 2022). "In addition, nutrient deprivation in the PDAC tumor microenvironment (TME) may drive KRAS-mutated cancer cells to be more dependent on lysosomal nutrient scavenging pathways, such as macropinocytosis and autophagy, to recycle energy and biosynthetic building blocks from the microenvironment." (PMID 36151074, 2022). "Hypermethylated CDH17 conferred high risk of disease recurrence and was associated with over-activity of oncogene signalling pathways, such as KRAS and low anti-tumour immune activity." (PMID 36612154, 2022). "On the other hand, downregulated genes in tumor from both the KRAS WT and mutant TCGA datasets were observed to be significantly associated with 3 MAPK‐related and 6 PI3K/Akt‐related GO : BP terms." (PMID 34919787, 2022). "Second, we analyzed the KRAS expression level with the characteristics of tumor patients, tumor stage, tumor microenvironment, and immune cell infiltration of 33 kinds of tumors; finally, we investigated the molecular mechanisms by GO and KEGG analysis." (PMID 36330448, 2022). "Pan-cancer analysis of KRAS indicated that 33 cancers had different expressions of these genes between normal and tumor samples." (PMID 35563733, 2022). "Further exploratory studies of MSH3, EMAST, KRAS and immune cell infiltration in the tumour microenvironment are indicated in SA CRC patients." (PMID 36280820, 2022).